CTLA4 (cytotoxic T-lymphocyte associated protein 4)
Diseases named in the same sentence as CTLA4 in open-access papers (continued):
Sharing a sentence is not in itself a finding about the gene and the disease.
cancer (continued). "Despite ICB showed excellent cancer therapy effects, and some inhibitors including anti-CTLA-4 and PD-L1 monoclonal antibodies have been approved by FDA, however, some limitations still exist such as high off-target, low objective response rate and the risk of immune-related side effects." (PMID 36733388, 2022). "Moreover, correlation between KIF15 and immune gene set was analyzed, and the expression of several important immune-related genes was significantly related to KIF15 expression level in pan-cancer, such as CTLA4, IDO1, and LAG3." (PMID 35359374, 2022). "Therefore, it is possible that propranolol and anti-CTLA4 synergistically stimulate the initial priming phase of an anti-cancer immune response, making this combination treatment particularly effective." (PMID 35017664, 2022). "CTLA-4 and PD-1 blockades therapies significantly improve survival rates in many cancer types." (PMID 36152044, 2022). "Notably, elevated PD1 or CTLA4 levels indicate an exhausted status of immune cells, which is a common occurrence in cancers." (PMID 35222383, 2022). "Furthermore, YST-OVH treatment modified the cancer-immune set point of tumors coupled to coexpression of CTLA-4 and TIM-3 on exhausted CD8+ T cells and high levels of CTLA-4+ Treg cells." (PMID 35688558, 2022). "The anti-tumor cellular mediated immune response is recovered, and the cancer cells could be removed from the immune system by the blockage of PD-1/PD-L1 and CTLA4/B7 checkpoints." (PMID 35008377, 2022). "Furthermore, TOP2A was positively associated with expression of immune checkpoints (CD274, CTLA4, HAVCR2, LAG3, PDCD1 and TIGIT) in most cancer types." (PMID 35778520, 2022). "This current study regarded CTLA4-PD-L1 DNA and protein vaccines as therapeutic cancer vaccines." (PMID 36341387, 2022). "Therefore, inhibitors of CD73 are currently used in combination with existing cancer therapies for cancer immunotherapy, including anti-PD-1/PD-L1 and anti-CTLA-4 therapies." (PMID 36159861, 2022). "Of note, CTLA4 and PD-1/PD-L1 are two major non-redundant immune checkpoints implicated in promoting cancer immune evasion, and ultimately lead to relapse." (PMID 36159789, 2022). "In this case, ICBs targeting PD-L1 may reach maximal efficacy in inhibiting the cell-autonomous pro-metastatic effects of PD-L1 in the cancer cells if they will be given alongside ICBs that prevent immune suppression by targeting PD-1 or CTLA-4." (PMID 35205789, 2022). "Thus, seven ICIs are currently in clinical use for cancer therapy, ipilimumab—targeting CTLA-4—pembrolizumab and nivolumab—targeting PD-1—and atezolizumab, avelumab, durvalumab, and cemiplimab, targeting PD-L1." (PMID 35399527, 2022). "Taken together, the CTLA4-PD-L1 chimeric protein vaccine may function both as a therapeutic cancer vaccine and as a preventive cancer vaccine in the TAA-induced iCCA rat model." (PMID 36341387, 2022). "Previous studies confirmed that CTLA-4, PD-1, and PD-L1 as immune checkpoints could prevent the immune system from killing cancer cells by inhibiting the autoimmunity." (PMID 35833141, 2022). "Since a CTLA-4 inhibitor, ipilimumab, has been approved by America food and drug administration against advanced-stage melanoma in 2011, ICIs have become a hotspot and have revoluted treatments of various cancers." (PMID 36699050, 2022). "Cancer treatment has been radically transformed by immunotherapies that can unleash antitumor immune responses, as highlighted by the utility of checkpoint blockade antibodies against PD-1/PD-L1 and CTLA-4." (PMID 35775486, 2022). "CTLA4 blockers have clinically been proven to improve the prognosis of cancer patients." (PMID 35401882, 2022). "Thus, treatment with anti-PD-1, anti-PD-L1, or anti-CTLA4 can reinvigorate T cells and make the adaptive immune system target cancer cells." (PMID 35884501, 2022). "In this study, KIF15 significantly related to CTLA4 expression in 17 out of 33 cancer types." (PMID 35359374, 2022).
cancer (continued). "Moreover, ICIs, including anti-CTLA-4 and anti-PD-1/PD-L1 antibodies, have successfully reinvigorated TILs and benefited a large number of cancer patients." (PMID 35320940, 2022). "Additional assessment is required to determine whether CTLA-4 ICB in the context of cancer vaccines improves clinical responses." (PMID 35651800, 2022). "Furthermore, CCNA2 is positively associated with expressions of immune checkpoints (CD274, CTLA4, HAVCR2, LAG3, PDCD1, and TIGIT) in most cancer types." (PMID 35480884, 2022). "Blood serum analysis after implantation showed that BC significantly reduced IgG as well as anti-CTLA-4 peak levels, as compared to mice that received IgG in free solution (more than 5-fold), which is a considerable factor of decrease in cancer drug delivery studies." (PMID 35890247, 2022). "Notably, many ongoing clinical trials are attempting to assess the application of TIGIT blockade or TIGIT blockade in combination with anti-PD-1/PD-L1, anti-CTLA-4 or anti-LAG-3 antibodies in the treatments for many cancers." (PMID 35320940, 2022). "Drugs targeting PD-1 and CTLA-4 have been approved for the treatment of different types of cancer." (PMID 35572541, 2022). "In recent years, the immunosuppressive role of the CD73/A2AR axis in cancer has been investigated, and the results suggest it may represent another attractive target complementing PD-1/PD-L1 and CTLA-4 blockade for antitumor immunotherapy." (PMID 35671108, 2022). "It has achieved great success to use CTLA-4 and PD-1 in cancer immunotherapy." (PMID 35281059, 2022). "This IDO/PD-L1/CTLA-4 interplay is associated with a negative prognosis of cancer patients, showing that the expression of IDO, PD-L1, and CTLA-4 is strongly interconnected." (PMID 36713558, 2022). "Therefore, anti-checkpoint (ICP) medicines targeting PD-1 or programmed cell death ligand 1 (PD-L1) and CTLA-4 have been licensed for the treatment of a variety of cancers." (PMID 35745630, 2022). "The cancer therapy, especially for RCC, has been revolutionized based on the use of immune checkpoint inhibitors with targets such as programmed death 1 (PD-1), PD-L1 and cytotoxic T-lymphocyte-associated protein 4 (CTLA-4)." (PMID 35406537, 2022). "Over the past decade, the application of immune checkpoint inhibitors (CPI) against immune checkpoints PD-1/PD-L1 and CTLA-4 have revolutionized cancer treatment, both increasing cancer survival time and leading to complete remission in a significant proportion of patients." (PMID 36923311, 2022). "The hypothesis that tumor genetics can influence immunotherapy response in patients with cancer was first observed in the setting of anti–CTLA-4 therapy for metastatic melanoma." (PMID 35703181, 2022). "Similarly, another study on 133 cancer patients revealed that a combination of focal palliative radiation and CTLA-4 and/or PD-1 inhibitors were well tolerated, with manageable irAEs." (PMID 35392976, 2022). "Most studies analyzing CTLA-4 in cancer have employed flow cytometry or RNA based methods." (PMID 35091676, 2022). "However, the interaction of CTLA-4 on naive T cells with CD80 on cancer cells produces an inhibitory signal for T cell activation, leading to the inhibition of T cell activation and suppression of the immune response." (PMID 36142412, 2022). "Malignant tumors may avoid immune destruction by activating immune checkpoint target genes (e.g., PD-1, PD-L1, CTLA-4, TGF-β, and HAVCR2)." (PMID 36275676, 2022). "Recently, ICIs such as anti-programmed cell death protein 1 (PD-1) antibodies, anti- programmed cell death ligand 1 (PD-L1) antibodies, and anti-CTLA-4 antibodies have contributed greatly to cancer therapy and have improved the prognosis of advanced cancer patients." (PMID 36421377, 2022). "In addition, anti–CTLA-4–triggered adverse events can be segregated from cancer immunotherapeutic effects." (PMID 35775486, 2022). "This is the case of CTLA-4 or PD-1, the two most broadly blocked targets in cancer immunotherapy." (PMID 36009389, 2022).
cancer (continued). "In recent years, immune checkpoint inhibitors (ICIs), represented by programmed cell death protein-1 (PD-1)/programmed cell death ligand 1 (PD-L1) and cytotoxic T lymphocyte-associated protein 4 (CTLA-4) monoclonal antibodies, have revolutionized the treatment of malignant tumors." (PMID 36225926, 2022). "Tumor suppression of T-cell activation via PD-1 and/or CTLA-4 is a major escape mechanism of cancer cells, and the possibility of unlocking this suppression revolutionized the treatment paradigm of many types of cancer, including SCCHN." (PMID 36611391, 2022). "Based on the subgroup analysis by ethnicity, CTLA-4 rs231775 polymorphism was observed to be significantly associated with lower cancer risks in Asians and Caucasians, but not Africans, suggesting genetic diversity across ethnic groups." (PMID 35600409, 2022). "Given the success of anti-PD1, anti-PDL1, and anti-CTLA4 treatments in cancer patients, we compared the difference in the expression value of immune checkpoints (including PD-1, PD-L1, and CTLA-4), and the different subgroups categorized by the median of TIMSig." (PMID 36120553, 2022). "Our study demonstrated that the RPM scores across 12 types of cancers were significantly associated with TMB, MSI, CD8+ T-cell infiltration, immune checkpoint molecules (PD-1/PD-L1, CTLA4), and cytokine (IFN-γ, TGF-β, and TNF-α) expression, which are key predictors of immunotherapy response." (PMID 35493519, 2022). "Moreover, it was also demonstrated that CTLA-4 expression is increased in MSI tumors compared to MSS cancers." (PMID 36072957, 2022). "Several PD-1/PD-L1 and CTLA-4 inhibitors have been approved for cancer treatments." (PMID 35443644, 2022). "In cancer, CTLA-4 mediated modulation of IL-4IL-4 is responsible for immune dysregulation." (PMID 35525950, 2022). "Most notably, ICIs targeting CTLA-4 or PD-L1/PD-1 have yielded remarkable clinical responses for a variety of cancer types, with a range of drugs currently approved targeting these axes available as cancer treatments." (PMID 35804934, 2022). "However, antibodies generated against CTLA-4 have been proposed as effective in the treatment of a variety of cancers." (PMID 35434132, 2022). "Alternatively, established cancer immunotherapies, such as anti-PD-1/PD-L1 and anti-CTLA-4, if used in combination with TLS neogenesis-inducing agents, might show enhanced effectiveness." (PMID 36551593, 2022). "Among these, CXCR2P1 has been speculated to be related to immune checkpoints PD-1, PD-L1, and CTLA4, which are crucial for successful cancer immunotherapy that contribute to the immune response, but there is still a lack of direct evidence." (PMID 36097539, 2022). "Immune checkpoint proteins, such as CTLA-4 and PD-1, prevent T cells from destroying cancer cells." (PMID 35632572, 2022). "Accordingly, a combination of high-dose Vit-C (4 g/kg) with anti-CTLA-4 (200 μg) and anti-PD-1 (250 μg) antibodies resulted in significant tumor impairment and remission via the infiltration and activation of anti-cancer adaptive immunity (CD8 T and CD4 T cells), especially CD8 T cells." (PMID 35745630, 2022). "Similar to the pan-cancer analysis, LRP2 mutations had high TMB, MSI and immune cell infiltration in EC and also leaded to high expression of immune-related genes, such as CXCL9, CXCR6, CXCL13, ICOS and immune checkpoint genes (CTLA4 and LAG3)." (PMID 35834061, 2022). "Immunotherapy with immune checkpoint inhibitors (ICIs), including anti-programmed cell death-1 (PD-1)/programmed cell death ligand-1 (PD-L1) antibodies and anti-cytotoxic T lymphocyte-associated protein 4 (CTLA-4), were recently demonstrated to improve the clinical outcome of certain cancers." (PMID 36212775, 2022). "Furthermore, immune checkpoint inhibitors have shown positive results in therapies for cancer, such as ipilimumab targeting CTLA4 and lambrolizumab targeting PD-1." (PMID 35189890, 2022).
cancer (continued). "Therefore, both CTLA-4 and PD-1 activation inhibit T cell activation and impair effector T cells cytotoxicity against cancer cells." (PMID 35011741, 2022). "Blocking CTLA-4 and PD-1 immunotherapies became a crucial part of cancer therapy." (PMID 35274175, 2022). "However, the cytotoxic T-lymphocyte-associated protein 4 (CTLA-4) and programmed cell death-1 (PD-1) receptors on the surface of the T-cell membrane are hyperactivated, which can help the cancer cells to evade the immune system." (PMID 35433823, 2022). "Checkpoint inhibitors targeting PD1, PD-L1 and CTLA-4 has improved survival in many cancers." (PMID 36061172, 2022). "The blockade of both targets, CTLA-4 and PD-1, currently constitutes the first line of cancer treatment along with the two classical treatments, chemo- and radiotherapy, which indicates the importance of novel discoveries trying to improve the efficacy of immunotherapy." (PMID 36009389, 2022). "For example, programmed cell death 1 (PD-L1), cytotoxic T lymphocyte antigen 4 (CTLA4), and the indoleamine 2, 3-dioxygenase 1 (IDO1) have achieved impressive success in the treatment of different cancer types, especially the combined treatment of PD-L1 and CTLA4." (PMID 35778697, 2022). "In conclusion, we have developed a CTLA4-PD-L1 chimeric protein vaccine, which may function both as a therapeutic cancer vaccine and as a preventive cancer vaccine in the TAA-induced iCCA rat model." (PMID 36341387, 2022). "Programmed cell death 1 (PD1): programmed cell death 1 ligand 1 (PDL1), and cytotoxic T lymphocyte-associated protein 4 (CTLA4): B-lymphocyte activation antigen B7 (B7-1; also termed CD80) are the most extensively studied immune checkpoints for cancer immunotherapy." (PMID 35493449, 2022). "Furthermore, risk score was linked to immune checkpoint expression (including PD-L1, CTLA4), targeted therapy gene expression (PARP, PDGFRA), cancer stem cell (CSC), chemotherapy and targeted medication sensitivity." (PMID 36307842, 2022). "A clinical follow-up study demonstrated that while anti-CTLA-4 immunotherapy promoted intra-tumoral Teff infiltration, it did not cause FoxP3+ T cell depletion in human cancers." (PMID 36142818, 2022). "Thus, we conclude that LS diet plus anti-CTLA4 mAb therapy exerted anti-cancer immunotherapeutic efficacy, improved the survival rate, and, at the same time, reduced the systemic irAE response." (PMID 35741331, 2022). "Importantly, this T cell subset also expresses CTLA-4 constitutively and thus is targetable by CTLA-4 blockade in cancer therapy." (PMID 36612283, 2022). "Moreover, immune checkpoint inhibitors (ICIs) targeting the programmed cell death 1 (PD-1), the cytotoxic T-lymphocyte associated antigen 4 (CTLA-4), and other immunotherapy approaches have become standards of care for many cancers." (PMID 35807269, 2022). "High expression of both PD-L1 and CTLA-4 can inhibit the activity of T cells, which may lead to a lack of immune response in cancer patients, resulting in immune evasion of cancer cells and promoting cancer cell proliferation." (PMID 36132144, 2022). "The discovery of the immune-checkpoint inhibitors [(ipilimumab, an anti-cytotoxic T lymphocyte-associated protein 4 (CTLA-4) antibody, programmed death 1 (PD-1) and programmed death-ligand 1 (PD-L1)], has placed immunotherapy to the front-line of cancer treatment, especially for advanced NSCLC." (PMID 36313656, 2022). "Since the Food and Drug Administration (FDA) approval of anti-CTLA-4 antibody ipilimumab in 2011, several antibodies targeting PD-1/programmed death-ligand 1 (PD-L1) immune checkpoint pathway have been approved for cancer therapy in various indications with many more in the pipeline." (PMID 35585982, 2022). "Furthermore, immunotherapy that block the inhibitory receptors PD-1 and CTLA-4 has been successful in the tratment of several cancers." (PMID 35236310, 2022). "Immunotherapies represented by PD-1/CTLA-4 inhibitors have been widely used in cancer therapy." (PMID 35342352, 2022).
cancer (continued). "Notably, CD274/PD-L1, PDCD1LG2/PD-L2, PDCD1/PD1, cytotoxic T lymphocyte-associated antigen 4 (CTLA4), T cell membrane protein 3 (TIM3; also known as HAVCR2), and lymphocyte activation gene 3 (LAG3) were correlated to FAM72A across different cancers." (PMID 36613817, 2022). "PA may have an impact on CTLA-4 (inhibitory immune checkpoint) and provide to better response to immunotherapy in cancer patients." (PMID 36077690, 2022). "The development of immune checkpoint inhibitors (ICIs) targeting cytotoxic T lymphocyte antigen 4 (CTLA-4) and programmed cell death-1/ligand (PD-1/PD-L1) significantly improved treatment of some cancers allowing a longer remission in those cases that previously were considered untreatable." (PMID 36121543, 2022). "PD-L1, PD-L2 and CTLA-4 are highly expressed across different cancer types." (PMID 36686160, 2022). "Hence, ICIs, including anti-PD-1 (nivolumab and pembrolizumab), anti-PD-L1 (durvalumab, avelumab, and atezolizumab), and anti-CTLA-4 (ipilimumab and tremelimumab) antibodies have been developed for cancer immunotherapy." (PMID 35892821, 2022). "● Inducing anti-cancer response by targeting PD-1/PD-L1, CTLA-4 of T cells." (PMID 36304546, 2022). "Antibodies against the checkpoint proteins PD-1 /PD-L1 and CTLA-4 may interrupt this process of immune escape and reactivate anti-cancer T-cell activity." (PMID 35448174, 2022). "In TME, the anti-cancer immune response is mediated primarily by CD8+ T cells, which are controlled by co-inhibitory signaling molecules, including programmed cell death protein 1 ligand 1 (PD-L1) and cytotoxic T lymphocyte-associated protein 4 (CTLA-4)." (PMID 35557959, 2022). "In addition, cell lines from various malignant tumors generate CTLA-4, which promotes apoptosis via interaction with its ligand." (PMID 35971106, 2022). "Anti-CTLA-4, PD-1, and PD-L1 inhibitors are the main types of checkpoint inhibitor immunotherapy drugs that have been developed and reported to be an efficient treatment for various malignant tumor types." (PMID 36046747, 2022). "Among these therapeutic drugs, ICIs targeted PD-1/PD-L1 and CTLA-4 have induced unprecedented responses in some patients with advanced cancers, nonetheless, the limited clinical response restricted the universal clinical application of ICB therapy across multiple cancers." (PMID 36159996, 2022). "Additionally, RT and other chemotherapeutic drugs have been shown to improve anti-cancer efficacy in PCa when CTLA-4 and PD-1/PD-L1 are inhibited." (PMID 36016257, 2022). "Immune checkpoint inhibitor (ICI) which enhances the antitumor activity of T cells by blocking the programmed cell death protein 1 (PD-1) or cytotoxic T lymphocyte antigen 4 (CTLA-4) pathways, has shown breakthroughs in cancer therapy and has been effective in the treatment of EC in recent years." (PMID 36568254, 2022). "CTLA-4 blockers prevent these inhibitions and allow cytotoxic T cells to kill cancer cells." (PMID 35265206, 2022). "CTLA4, a membrane receptor of T cells, can combine with B7 molecules to induce inhibitory signals and suppress T cell activation, weakening its ability to kill cancer cells." (PMID 35710350, 2022). "We assessed whether NMNG alterations could predict patient responses to ICIs in the context of the recent approval of drugs that target PD-1 and CTLA-4 for the treatment of various types of cancers." (PMID 36726460, 2022). "Moreover, the FAM72Alow group was more likely to benefit from anti-PD1/PDL1/PDL2, anti-CTLA4, and combined immunotherapies in various cancers." (PMID 36613817, 2022). "The CTLA-4 pathway is a commonly targeted pathway in cancer immunotherapy." (PMID 35091676, 2022). "In a previous study, CTLA4, PD-1, and PD-L1, as the checkpoint molecules, could be targeted by antibodies to slow cancer progression." (PMID 35778697, 2022).